MACC1-AS1 (MACC1 antisense RNA 1)
Gene: Long non-coding RNA gene on chromosome 7 (20,121,053 to 20,153,542, forward strand). Ensembl gene ENSG00000228598.
Diseases named in the same sentence as MACC1-AS1 in open-access papers:
MACC1-AS1 is named in the same sentence as 2 diseases in open-access papers, as found by Europe PMC text mining. Sharing a sentence is not in itself a finding about the gene and the disease. The quoted sentences say what the papers report.
gastric cancer (1 paper, 2021). A primary or metastatic malignant neoplasm involving the stomach. "In gastric cancer (GC), evidence presents that MSCs secreted TGF-β1 promotes fatty acid oxidation (FAO) to support stemness features and drug resistance, which is mediated by activating SMAD2 and SMAD3 and promoting lncRNA MACC1AS1 expression." (PMID 34095111, 2021).
nasopharyngeal carcinoma (1 paper, 2021). A carcinoma arising from the nasopharyngeal epithelium. "A similar ceRNA‐related mechanism has been reported in nasopharyngeal cancer, wherein MACC1 antisense RNA 1 (MACC1‐AS1) acts as a molecular sponge of miR‐145." (PMID 33512745, 2021).